FXR1 (FMR1 autosomal homolog 1)
Diseases named in the same sentence as FXR1 in open-access papers (continued):
Sharing a sentence is not in itself a finding about the gene and the disease.
oral cancer (9 papers, 2016 to 2024). "As expected, FXR1 overexpression is associated with poor prognosis of human oral cancers, according to TCGA analysis reported by us." (PMID 31940341, 2020). "Our data provide a molecular explanation for why oral cancer patients have loss-of-function in p21 and poor patient survival, where FXR1 and miR301a-3p are overexpressed in HNSCC patients." (PMID 31940341, 2020). "To investigate the association between FXR1 and mature miR301a-3p in oral cancer cells, we used RNA-IP (RNA immunoprecipitation) as described by us." (PMID 31940341, 2020). "Therefore, we set out to determine whether FXR1 directly associates with miR301a-3p and stabilizes its levels in oral cancer cells." (PMID 31940341, 2020). "Our previous findings demonstrated that overexpressed FXR1 in metastatic oral cancer cells (UMSCC-74A, -74B) and lung adenocarcinoma A549 cells contribute to tumor growth and proliferation." (PMID 38709899, 2024). "In FXR1-deficient cells, PNPT1 degrades miR301a-3p, increasing p21 protein translation and consequent oral cancer cell senescence." (PMID 38238286, 2024). "Chromosome 3q amplification in lung and oral cancer patients leads to an increase in FXR1 mRNA levels and exert oncogenic properties." (PMID 38709899, 2024). "Targeting FXR1-miRNA-mediated p21 regulation can inhibit the growth and proliferation of oral cancer." (PMID 38238286, 2024). "PRMT5i treatment had little effect on FXR1 mRNA, but it elevated p21 levels significantly in oral cancer cells." (PMID 38709899, 2024). "According to the TCGA analysis, patients with oral cancer who overexpressed FXR1 had poorer outcomes." (PMID 38238286, 2024). "Numerous observations in the manuscript suggest that FXR1 regulates the stability of miR301a-3p in oral cancer cells." (PMID 31940341, 2020). "Previously, we have shown that FXR1 targets p21 for its degradation and consequently to bypass cellular senescence and promote the proliferation of oral cancer cells." (PMID 31940341, 2020). "Firstly, to determine if miR301a-3p is regulated by FXR1, we used multiple oral cancer cell lines and tested the expression of miR301a in FXR1-depleted cells." (PMID 31940341, 2020). "Here, by small RNAseq, we show that RBP FXR1 controls the expression of a subset of mature miRNAs, including highly expressed miR301a-3p in oral cancer cells." (PMID 31940341, 2020). "To delineate if an increase in substrate (p21) concentration in the FXR1 knockdown cells can consume or reduce the pool of miR301a-3p, we ectopically expressed p21 in oral cancer cells and tested the expression of miR301a-3p." (PMID 31940341, 2020). "The data here provides evidence that FXR1 bound with miR301a-3p is protected from PNPT1 mediated degradation in oral cancer cells." (PMID 31940341, 2020). "In this report, we describe a pathway of miRNA regulation in which FXR1 represses PNPT1-mediated degradation in oral cancer cells." (PMID 31940341, 2020). "The qRT-PCR analyses indicated that miR301a-3p was significantly down-regulated in FXR1-depleted multiple oral cancer cells compared to control cells." (PMID 31940341, 2020). "This mode of action of FXR1 enhances the levels of miR301a and its oncogenic functions in oral cancer cells." (PMID 31940341, 2020). "Conversely, our findings suggest that PNPT1 mediated degradation of miR301a in HNSCC can be protected by FXR1, leading to the repression of p21 aiding to poor prognosis of oral cancer." (PMID 31940341, 2020). "We also observed that miR-29b was down-regulated along with miR301a-3p in FXR1 knockdown cells, suggesting that FXR1 is vital for a subset of oncogenic miRNA levels in oral cancer cells to regulate specific mRNA targets." (PMID 31940341, 2020).
oral cancer (continued). "We also show that miR301a-3p targets p21, and FXR1 knockdown leads to down-regulation of miR301a-3p and up-regulation of p21 mRNA and protein levels in multiple oral cancer cells." (PMID 31940341, 2020). "Together, our observations explain why over-expression of FXR1 and miR301a-3p in the oral cancer patient cohort lead to the downregulation of p21 signaling." (PMID 31940341, 2020). "The effect of FXR1 and miR301a-3p on p21 regulation suggests that genetic changes in the expression of these genes can induce oral cancer progression by decreasing the expression of p21." (PMID 31940341, 2020). "Altogether, these data indicate that silencing of FXR1 promotes the expression of p21 in oral cancer cells." (PMID 27606879, 2016). "Once FXR1 is amplified in oral cancer cells, protein p21 is suppressed and non-coding RNA TERC expression is aided, resulting in reduction of cellular senescence and promotion of cancer growth." (PMID 27606879, 2016). "To further confirm that FXR1 is a key regulator of senescence in these oral cancer cell lines and it does so by modulation p21 and TERC RNA, we set up the following experiment." (PMID 27606879, 2016). "In this report, we have identified that FXR1, overexpressed in oral squamous cell carcinoma, binds and destabilizes G4 containing RNA p21 and in turn reduces its protein expression in oral cancer cells." (PMID 27606879, 2016). "Overexpressed FXR1 binds and destabilizes p21 mRNA, subsequently reduces p21 protein expression in oral cancer cells." (PMID 27606879, 2016). "A significant decrease in number of viable cells is observed in both UMSCC74A (p<0.05) and UMSCC74B (p<0.01) cells with FXR1 KD compared to control, indicating FXR1 plays a key role in oral cancer cell viability and/or survival." (PMID 27606879, 2016). "Collectively, our analyses indicate that silencing of FXR1 in oral cancer cells led to DNA damage, cell cycle arrest and cellular senescence." (PMID 27606879, 2016). "In this report, we show that knockdown of RBP FXR1 is a major factor involved in cell cycle arrest and promoting cellular senescence through turnover of two distinct RNA targets in oral cancer cells." (PMID 27606879, 2016). "Thus, FXR1’s structural characteristics and affinity for RNAs preferentially G4 regions provide new insights into the molecular mechanism of FXR1 in oral cancer cells." (PMID 38709899, 2024). "FXR1 knockdown alters the expression of several miRNAs in both positive and negative oral cancer cells, inhibiting the expression of miR301a-3p and miR29b-3p in different oral carcinoma cells." (PMID 38238286, 2024). "In addition, it has been shown that p21 is a target of miR301a-3p and that when FXR1 is knocked out, miR301a-3p is downregulated while p21 mRNA and protein expression levels are elevated in different oral cancer patients." (PMID 38238286, 2024). "In oral cancer cells, FXR1 stabilized miR-301a-3p and miR-301a-3p, both of which target p21." (PMID 35886008, 2022). "Interestingly, in oral cancer cells, FXR1 stabilized miR-301a-3p, and these events reduced expression of p21." (PMID 34946859, 2021). "First, FXR1 knockdown leads to a change in levels of many miRNAs both positively and negatively in oral cancer cells, including decreased levels of miR29b-3p and miR301a-3p in multiple oral cancer cell lines." (PMID 31940341, 2020).
oral cancer (continued). "Through FXR1-mediated small RNA sequencing, we unexpectedly found that FXR1 stabilizes miR301a-3p, which in turn targets tumor suppressor p21 and blocks its expression in oral cancer cells." (PMID 31940341, 2020). "In this report, we find that mutating the miR301a-3p binding sites, that are also in the FXR1 binding region, in the p21 3’-UTR resulted in increased luciferase activity in the presence of FXR1, suggesting that both FXR1 and miR301a-3p are required to repress p21 in oral cancer cells." (PMID 31940341, 2020). "Together, these findings suggest that FXR1 controls the balance of miR301a-3p in oral cancer cells." (PMID 31940341, 2020). "To determine the biological role of FXR1-mediated regulation of miR301a, we examined whether miR301a-3p targets mRNA(s) that are known FXR1 targets in oral cancer cells." (PMID 31940341, 2020). "To investigate whether FXR1-mediated p21 degradation requires miRNA- and RNA-induced silencing complex, we identified the miRNAs that are controlled by FXR1 in oral cancer cells." (PMID 31940341, 2020). "Our data suggest that FXR1 represses PNPT1-mediated degradation of miR301a-3p in oral cancer cells." (PMID 31940341, 2020). "To determine whether miR301a-3p levels were reduced in the FXR1 knockdown cells due to increased degradation, we measured the level of miR301a-3p in control and FXR1 knockdown oral cancer cells." (PMID 31940341, 2020). "Thus, our work illustrates the unique role of FXR1 that is critical for the stability of a subset of mature miRNAs or at least miR301a-3p to target p21 in oral cancer." (PMID 31940341, 2020). "An equally steady decrease of both TERC and FXR1 is observed under FXR1 depleted oral cancer cells." (PMID 27606879, 2016). "FXR1 KD has induced the expression of p21 in both the oral cancer cell lines." (PMID 27606879, 2016). "Thus, silencing of FXR1 in oral cancer cells facilitates an increase in steady-state level of p21 and subsequently promotes its protein expression, indicates that overexpressed FXR1 in HNSCC destabilizes p21 mRNA and reduces its protein expression." (PMID 27606879, 2016). "FXR1 KD induces cell cycle arrest in G0/G1 providing evidence that FXR1 might regulate cell division in oral cancer." (PMID 27606879, 2016). "In addition, silencing of FXR1 in multiple oral cancer cells also promotes senescence by positive SA-β-gal staining." (PMID 27606879, 2016). "Interestingly, PRMT1-silenced cells did not change the protein levels of FXR1 or FXR2, indicating that FXR1 may be a direct substrate of PRMT5 in oral cancer cells." (PMID 38709899, 2024). "Our published findings show that FXR1 specifically targets the G4-rich regions of p21 mRNA and TERC long non-coding RNA to control their expression in oral cancer cells." (PMID 38709899, 2024). "Overexpression of FXR1, an RNA-binding protein, has been reported in a wide range of cancers, including HNSCC and oral cancer." (PMID 34946859, 2021). "Together, our previously published results and the data presented here suggest that both FXR1 and miR301a-3p are amplified in HNSCC tumor samples, and FXR1 controls the expression of mature miR301a-3p in oral cancer cells." (PMID 31940341, 2020). "We provide evidence that miR301a-3p expression is rescued by downregulation of both FXR1 and exoribonuclease PNPT1 in oral cancer cells suggesting that FXR1 acts as a stabilizing factor for miR301a-3p against PNPT1." (PMID 31940341, 2020). "The effect of FXR1, PNPT1, and miR301a-3p expression suggests that the miRNA-mediated p21 regulation can be targeted to reduce the growth and proliferation of oral cancers." (PMID 31940341, 2020). "Here, we silenced FXR1 and estimated the level of γ-H2AX and pATM foci in both oral cancer cell lines." (PMID 27606879, 2016). "Taken together, these data indicate that FXR1-regulated repression of senescence involves both down-regulation of p21 and up-regulation of TERC in oral cancer cells." (PMID 27606879, 2016).
oral cancer (continued). "The pre-miR301a level did not change in most of the FXR1-depleted cells, except Cal27, indicating that only mature miR301a-3p is dependent on FXR1 in most of the oral cancer cells." (PMID 31940341, 2020). "miR301a-3p level goes down in the absence of FXR1, increasing p21 to suppress the growth of oral cancer cells." (PMID 31940341, 2020). "To determine whether FXR1-mediated miR301a-3p stabilization is coordinated by exonucleases that are present or aberrantly expressed in HNSCC, we tested their levels in oral cancer cells and A549 cells in comparison with normal human oral keratinocyte (HOK)." (PMID 31940341, 2020). "Exoribonuclease PNPT1 degrades miR301a-3p in the absence of FXR1 in oral cancer cells, and the degradation is rescued in the FXR1 and PNPT1 co-knockdown cells." (PMID 31940341, 2020). "Taken together, these data indicate that FXR1-regulated senescence is not reversible in oral cancer cells, even after expressing FXR1 back into the cultured cells." (PMID 27606879, 2016). "Overexpression of p21 did not alter the levels of FXR1 or miR301a-3p in the oral cancer cells tested here, suggesting that consumption of miR301a-3p or feedback regulation of p21-mediated control of either miR301a or FXR1 was not occurring in the oral cancer cells." (PMID 31940341, 2020). "In the absence of FXR1, miR301a-3p is degraded by PNPT1, increasing p21 protein translation, and in turn, promoting cellular senescence of the oral cancer cells." (PMID 31940341, 2020).
breast carcinoma (8 papers, 2017 to 2025). "FXR1 overexpression is associated with worse disease-specific disease-free survival in the METABRIC breast cancer cohort and worse overall survival in the TCGA cohort." (PMID 34044876, 2021). "Similar to the results of this study, FXR1 is highly abundant in ovarian and breast cancer, and is associated with poor prognosis." (PMID 30691465, 2019). "Furthermore, a high FXR1 expression level is associated with more severe features and worse survival outcomes in ductal breast cancer patients." (PMID 38238286, 2024). "Our findings highlight FXR1 as a promising therapeutic target to improve existing therapeutic regimes for ER+ breast cancer patients." (PMID 40196843, 2025). "FXR1-mediated post-transcriptional modulation of ARID1A also increased radiation therapy resistance in breast cancer cells." (PMID 38238286, 2024). "What we have done here indicated that ENST00000508435 participated in promoting migration of breast cancer by interacting with FXR1." (PMID 34057025, 2021). "Finally, we provide proof-of-concept evidence supporting FXR1 antagonism as a potential treatment for bone metastases in ER+ breast cancer." (PMID 40196843, 2025). "FXR1, as an RNA-binding protein, plays a vital role in breast cancer progression and cell invasion." (PMID 34044876, 2021). "Taken together, we propose that ENST00000508435 regulates FXR1 to promote breast cancer metastasis." (PMID 34057025, 2021). "In our study, overexpression of ENST00000508435 significantly increased migration of MDA-MB-231 cells, which was inhibited by depletion of FXR1, supporting that the function of ENST00000508435 in breast cancer migration depends on FXR1." (PMID 34057025, 2021). "After quantitative calculation, the levels of serum CCL18 and CXCL1 antigens, and C1D, TM4SF1, FXR1, and ZNF573 IgG autoantibodies were significantly higher in patients with OC than in those with cervical cancer, liver cancer, breast cancer, gynecological benign tumor patients, and healthy women." (PMID 34995016, 2022). "Here, our work shows that lncRNA ENST00000508435 significantly promotes breast cancer metastasis, and we initially report that the effect of ENST00000508435 is mediated by FXR1, which is co-expressed and positively correlated with ENST00000508435 in breast cancer cell lines and tissues." (PMID 34057025, 2021). "We also analyzed the relationship between expression of FXR1 and clinical pathological parameters [tumor size, breast cancer biomarkers (ER, PgR and HER2), lymph node metastasis, ki67 and Nottingham grade], and found that the expression of FXR1 was positively correlated with lymph node metastasis." (PMID 34057025, 2021).
autism (6 papers, 2015 to 2025). Persistent deficits in social interaction and communication and interaction as well as a markedly restricted repertoire of activity and interest as well as repetitive patterns of behavior. "Previous studies have indicated that several differential alternative splicing genes (DAS), such as FXR1, C19orf2, GSN, and SRPK1, are associated with autism." (PMID 28000768, 2016). "FXR1 has been shown to be involved in RNA editing of autism-related genes." (PMID 39753370, 2025). "To conclude, in all three replication samples, we confirmed the association of the 8‐SNP model, derived from the broader fragile X gene family (FMR1, FXR1, FXR2, FMR2), with autism‐related behaviors, underlining the phenotypical continuum of these traits across health and disease." (PMID 26612855, 2015).
head and neck cancer (6 papers, 2017 to 2024). A primary or metastatic malignant neoplasm affecting the head and neck. "It is also vital to show in this study that FXR1 prefers the G4-mRNAs in head and neck cancer cells, mostly localized in the cytoplasm." (PMID 38709899, 2024). "We found that FXR1 was predominantly upregulated in 10 out of 14 cancer types, including lung squamous cell carcinoma, lung adenocarcinoma, kidney clear cell carcinoma, stomach cancer, rectal cancer, liver cancer, head and neck cancer, colon cancer, bile duct cancer, and esophageal cancer." (PMID 35194031, 2022). "To determine whether FXR1-targeted miRNAs were differentially expressed in HNSCC, we utilized The Cancer Genome Atlas (TCGA) data for Head and Neck cancer utilizing the University of California Santa Cruz (UCSC) functional genomics browser, XENA." (PMID 31940341, 2020).
lung squamous cell carcinoma (6 papers, 2014 to 2023). "Vulnerability of cancer cells to ACTL6A or FXR1 knock-out would be necessary to characterize the role of these genes in lung squamous cell carcinoma." (PMID 25484917, 2014). "Integrative genomic analysis pointed at genes involved in ubiquitylation pathway as candidate drivers, while microarray expression profiles indicated that FXR1 was one of three genes from the amplicon consistently overexpressed in lung squamous cell carcinoma." (PMID 25484917, 2014). "FXR1 has been previously shown to be upregulated in head and neck and lung squamous cell carcinoma." (PMID 35194031, 2022). "FXR1 has been previously shown to be an oncogene in head and neck and lung squamous cell carcinoma." (PMID 31940341, 2020). "FXR1 is over-expressed in multiple cancers, including head and neck (HNSCC) and lung squamous cell carcinomas (LSCC)." (PMID 31940341, 2020). "The co-amplification of FXR1, protein kinase C, iota (PRKCI), and epithelial cell transforming 2 (ECT2) is detected in lung squamous cell carcinoma (LSCC) tissues; biologically, Fxr1 forms a complex with PRKCI and ECT2 to promote cell proliferation and invasion." (PMID 35565262, 2022).